SIRT3 (sirtuin 3)
Diseases named in the same sentence as SIRT3 in open-access papers (continued):
Sharing a sentence is not in itself a finding about the gene and the disease.
lipodystrophy (1 paper, 2021). A congenital or acquired disorder characterized by abnormal loss or redistribution of the adipose tissue in the body. "In mice, treatment with Shizophyllan resulted in an increased SIRT3 expression and activation, which in turn resulted in less complications from a lipodystrophy model in mice." (PMID 33806509, 2021). "In mice, treatment with schizophyllan results in an increased SIRT3 expression and activation of the brown adipose tissue, which in turn results in reduced complications in a mouse lipodystrophy model." (PMID 33806509, 2021).
mesothelioma (1 paper, 2019). A usually malignant and aggressive neoplasm of the mesothelium which is often associated with exposure to asbestos. "SIRT3 and SIRT5 exhibited pro-survival effects in U2OS cells, whereas in mesothelioma cell lines SIRT3 and SIRT5 exerted pro-survival trends." (PMID 31608237, 2019). "Reduced cell viability was also observed in mesothelioma cells treated with rotenone and etoposide, as well as in resveratrol treated Mero-14 cells in which SIRT3 had been silenced." (PMID 31608237, 2019). "In mesothelioma cell lines, SIRT3 and SIRT5 exerted pro-survival trends." (PMID 31608237, 2019). "Analysis of sirtuin family members crosstalk revealed that SIRT1 has negative effect on SIRT3 and SIRT5 protein levels in bone cells and this depends on the type of cellular stress, whereas positive effects were recorded in Mero-14 mesothelioma cells." (PMID 31608237, 2019).
migraine (1 paper, 2023). "However, until now, no study has explored the role of Sirt3 on migraine." (PMID 37271805, 2023).
multiple myeloma (1 paper, 2024). "In patients with multiple myeloma, a reduction in SIRT3 levels alongside elevated clinical markers of inflammation may be significant in the development of treatment-related peripheral neuropathy." (PMID 39727710, 2024). "Furthermore, decreased SIRT2 and SIRT3 concentrations have been correlated with disease progression and increased redox imbalance in multiple myeloma patients." (PMID 39727710, 2024).
multiple system atrophy (1 paper, 2025). Multiple system atrophy (MSA) is a neurodegenerative disorder characterized by autonomic failure (cardiovascular and/or urinary), parkinsonism, cerebellar impairment and corticospinal signs with a median survival of 6-9 years. "However, no literature was retrieved on the relationship between SIRT3 and multiple system atrophy (MSA)." (PMID 40969935, 2025).
neuritis (1 paper, 2020). A neuropathy arising from inflammation of one or more nerves. "NR also has been shown to prevent the noise-induced hearing loss and the neuritis withdrawal from hair cells in the internal ear through a SIRT3-dependent mechanism." (PMID 31929756, 2020).
oligoasthenoteratozoospermia (1 paper, 2022). A form of male infertility that is characterized by a combination of low number or oligozoospermia, poor motility or asthenozoospermia, and abnormal shape or teratozoospermia of sperms. "Our results concerning seminal plasma SIRT3 concentrations indicate that teratozoospermia and oligoasthenoteratozoospermia are associated with decreased levels of this enzyme." (PMID 36142505, 2022). "Decreased SP SIRT3 concentrations may be associated with teratozoospermia and oligoasthenoteratozoospermia." (PMID 36142505, 2022).
oligospermia (1 paper, 2024). Decreased number of spermatozoa in the semen. "The aim of the present study is to determine the role of SIRT1 and SIRT3 in regulating oxidative stress, telomere shortening, and their association with oligospermia." (PMID 38255792, 2024). "Our results support the hypothesis that various sperm parameters in the state of oligospermia are associated with or caused by reduced levels of SIRT1 and SIRT3 proteins." (PMID 38255792, 2024). "Therefore, we assessed the protein levels of SIRT1 and SIRT3, total antioxidant capacity (TAC), superoxide dismutase (SOD), malondialdehyde (MDA) and catalase activity (CAT) in the seminal plasma of 272 patients with oligospermia and 251 fertile men." (PMID 38255792, 2024).
Osteolysis (1 paper, 2021). Osteolysis refers to the destruction of bone through bone resorption with removal or loss of calcium. "Moreover, Inhibition of SIRT3 prevents the pathological bone destruction by reducing the excessive activation of osteoclasts in the Ti particle-induced mouse osteolysis model." (PMID 33867853, 2021).
osteomyelitis (1 paper, 2026). An acute or chronic inflammation of the bone and its structures due to infection with pyogenic bacteria. "Serum SIRT1, SIRT3, apelin, and ELA levels were significantly lower in the DFI group and showed inverse correlations with HbA1c, PEDIS stage, disease duration, osteomyelitis, and inflammatory markers." (PMID 42195360, 2026).
Osteopenia (1 paper, 2016). Osteopenia is a term to define bone density that is not normal but also not as low as osteoporosis. "Mice deficient in SIRT3 exhibited severe osteopenia owing to increased numbers of osteoclasts." (PMID 26928655, 2016).
ovarian dysfunction (1 paper, 2023). The inability of the ovaries to function. "Our study confirmed metformin could not only improve body weight and metabolism disorders, but also improve ovarian dysfunction in PCOS mice.In addition, we explored metformin could regulate ferroptosis to improve PCOS via the SIRT3/AMPK/mTOR pathway." (PMID 36755918, 2023).
ovarian tumors (1 paper, 2019). "At least one copy of the SIRT3 gene was deleted in 40% of breast and OCs, and focal deletions of SIRT3 were especially frequent in ovarian tumors." (PMID 31572453, 2019).
periodontitis (1 paper, 2022). An acute or chronic inflammatory process that affects the tissues that surround and support the teeth. "Moreover, studies have shown that SIRT3 KO aggravated age-related alveolar bone loss, but the role of SIRT3 activation in treating periodontitis is still largely unknown." (PMID 36060706, 2022).
pneumonia (1 paper, 2017). An acute, acute and chronic, or chronic inflammation focally or diffusely affecting the lung parenchyma, caused by an infection in one or both of the lungs (by bacteria, viruses, fungi, or mycoplasma.). "In a preliminary experiment using a limited number of males (seven animals), the survival of SIRT3+/+ and SIRT3−/− mice to Klebsiella-induced pneumonia was not different." (PMID 28634345, 2017). "SIRT3+/+ and SIRT3−/− mice survived equivalently to non-severe pneumonia induced by K. pneumoniae (82.5% vs 93%, P = 0.4)." (PMID 28634345, 2017).
postmenopausal osteoporosis (1 paper, 2025). Metabolic disorder associated with fractures of the femoral neck, vertebrae, and distal forearm. "In this setting, SIRT3 acts as a mediator of estrogen-dependent bone loss—a potential target in postmenopausal osteoporosis, where hormonal decline and mitochondrial stress intersect." (PMID 41465170, 2025). "Contrary to protective effects observed in all other tissues SIRT3 mediates estrogen-dependent bone loss, with its absence mitigating age- and hormone-related bone deterioration, particularly in females, making it a potential target in postmenopausal osteoporosis." (PMID 41465170, 2025).
premature ovarian failure (1 paper, 2024). "The adaptive response of SIRT3 to gonadotoxic damage accentuates its potential role in preserving oocyte function and preventing premature ovarian failure." (PMID 39329773, 2024).
Salmonella Infections (1 paper, 2024). Infections with bacteria of the genus SALMONELLA. "Since SIRT1 and SIRT3 played an immunemodulatory role in Salmonella infection, we investigated whether Salmonella infection is associated with a shift in macrophage polarization status." (PMID 39693143, 2024). "Overall, our study highlights the crucial role of SIRT1 and SIRT3 in governing the host immune-metabolic shift during Salmonella infection, which in turn is vital for maintaining Salmonella metabolism." (PMID 39693143, 2024). "Together, this study highlights the complex and multifaceted nature of host–pathogen interactions, and the need for further research to fully understand the role of SIRT1 and SIRT3 in the context of Salmonella infection." (PMID 39693143, 2024). "This indicates the possible role of SIRT1 and SIRT3 in the regulation of cytokine production upon Salmonella infection." (PMID 39693143, 2024).
sarcoma (1 paper, 2019). A usually aggressive malignant neoplasm of the soft tissue or bone.
Seizure (1 paper, 2022). A seizure is an intermittent abnormality of nervous system physiology characterized by a transient occurrence of signs and/or symptoms due to abnormal excessive or synchronous neuronal activity in the brain. "Our and others’ finding of decreased level of SIRT3 after chronic seizures provides further strong support for the significance of the brain energy metabolism in epileptic seizures, as many mitochondrial enzymes involved in energy production are acylated." (PMID 36293175, 2022).
serous ovarian cancer (1 paper, 2019). "In present study, we found that SIRT3 is an independent predictor of better OS in serous ovarian cancer." (PMID 31113446, 2019). "In conclusion, SIRT3 was an independent favorable prognostic factor for OS in serous ovarian cancer, and added prognostic value to the traditional clinicopathological factors used to evaluate patients’ prognosis." (PMID 31113446, 2019).
status epilepticus (1 paper, 2025). Status epilepticus is defined as a continuous seizure lasting more than 30 min, or two or more seizures without full recovery of consciousness between any of them. "On the other hand, Sirtuin3 (Sirt3), a nicotinamide adenine dinucleotide-dependent enzyme, regulates astrocyte activation by attenuating Notch1 signaling, thereby contributing to the inflammatory response following status epilepticus." (PMID 40019515, 2025).
synovial sarcoma (1 paper, 2022). "In addition, miR-761 is closely associated with SIRT3-mediated chemical resistance, and changes in miR-761 abundance targeted SIRT3 to modulate the response of synovial sarcoma cells to pazopanib." (PMID 35832551, 2022).
synovitis (1 paper, 2020). Inflammation of a synovial membrane. "There is still a question regarding how SIRT3 decreases inflammation and oxidative stress in OA synovitis." (PMID 33062145, 2020). "It is proposed that OLA has therapeutic potential in OA synovitis, and the targeting of SIRT3 may be a potential therapeutic treatment to combat OA synovitis." (PMID 33062145, 2020). "This study aims at ascertaining whether SIRT3 is involved in OA synovitis." (PMID 33062145, 2020).
T-cell leukemia (1 paper, 2020). A malignant disease of the T-lymphocytes in the bone marrow, thymus, and/or blood. "Here, we identified a unique HDACi that possessed a potent anti-T cell leukemia activity by direct binding to and stabilization of SAP18, leading to downregulation of SIRT3 transcription through activation of the SAP18/SIN3 suppressor complex, resulting in apoptotic cell death." (PMID 33273692, 2020).
tuberculosis (1 paper, 2021). A chronic, recurrent infection caused by the bacterium Mycobacterium tuberculosis. "Relevance to tuberculosis disease in vivo was indicated by greater bacterial burden and immune pathology in M. tuberculosis-infected Sirt3−/− mice." (PMID 33531400, 2021). "Since our in vitro data identified SIRT3 as a regulator of metabolic reprogramming in M. tuberculosis-infected macrophages in vitro, we sought to determine whether this was recapitulated in vivo and whether it was associated with altered TB susceptibility." (PMID 33531400, 2021). "Taken together, our study provides evidence that downregulation of SIRT3 is important in the metabolic perturbation that occurs in macrophages following M. tuberculosis infection and that this impacts TB pathogenesis." (PMID 33531400, 2021). "We propose that SIRT3 modulation by M. tuberculosis is a key upstream event leading to metabolic reprogramming and macrophage dysfunction in tuberculosis (TB)." (PMID 33531400, 2021). "Based on our in vitro data and reports on the Warburg effect in TB, we predicted that reduced SIRT3 expression would contribute to excessive inflammation and a permissive environment for M. tuberculosis in the lung." (PMID 33531400, 2021).
type 2 diabetic nephropathies (1 paper, 2022). "We previously showed that, in BTBR ob/ob mice that develop type 2 diabetic nephropathy, renal Sirt3 mRNA expression and activity were reduced and associated with increased oxidative stress and mitochondrial structure and function abnormalities." (PMID 35955472, 2022). "We previously found that renal Sirt3 expression and activity were reduced in mice with type 2 diabetic nephropathy associated with oxidative stress and mitochondrial abnormalities and that a specific SIRT3 activator improved renal damage." (PMID 35955472, 2022).
uveal melanoma (1 paper, 2023). A melanoma derived from melanocytes of the uveal tract. "Our findings suggest that SIRT3 may act as a protective factor in the development of uveal melanoma, which is similar to previous findings." (PMID 37362244, 2023).
vascular dementia (1 paper, 2024). A degenerative vascular disorder affecting the brain. "GAS has been demonstrated to enhance mitochondrial respiration and dynamics and reverse mitochondrial dysfunction in vascular dementia by inhibiting the sirtuin 3 (Sirt3)-mediated transcription factor A acetylation pathway." (PMID 39776583, 2024).
venous thromboembolism (1 paper, 2017). Occlusion of the lumen of a vein by a thrombus that has migrated from a distal site via the blood stream. "SERPINE1 has been linked with a risk of venous thromboembolism, while SIRT3 was related to mitochondrial dysfunction." (PMID 28768485, 2017).
tumor (305 papers, 2006 to 2026). "Mechanistically, SIRT3 deficiency promotes IEC functions through quinolinic acid (QA)-mediated NAD+ synthesis for limiting tumor growth." (PMID 41487042, 2026). "IHC staining of the tumor tissues showed that the RCC1 knockdown caused an increase in SIRT3 protein expression in vivo." (PMID 41391757, 2025). "In PDAC, the dysregulation of SIRT3 has been linked to enhanced tumor proliferation, invasion and metastasis, through miRNA-708-5p." (PMID 39682281, 2024). "Downregulation of SIRT3 has been shown to be negatively associated with tumor size, TNM stage, and metastasis in previous studies." (PMID 39501597, 2024). "The low cytoplasmic expression of SIRT3 was significantly associated with more aggressive tumor phenotypes and reduced patient survival, indicating its crucial role in mitigating tumor progression." (PMID 39682281, 2024). "Analysis of the correlation of SIRT3 levels with clinicopathological data for patients with CRC showed that low SIRT3 expression was positively associated with tumor depth of invasion (P = 0.012), lymphatic metastasis (P = 0.000) and TNM stage (P = 0.000)." (PMID 36594098, 2023). "Regarding SIRT3 expression, it showed significant associations with apoptotic and mitotic indices, tumour extent, tumour stage and response to therapy (P = 0.022, 0.02, 0.042, 0.039 and 0.027)." (PMID 37996927, 2023). "In present study significant upregulation of SIRT3 was observed and this upregulation was found linked to the tumor aggressiveness and poor survival." (PMID 36809279, 2023). "This study showed a significant association between ARK5 and SIRT3 expression in tumour cells of RCC." (PMID 37996927, 2023). "SIRT3 expression in the studied cases was significantly associated with impaired tumour response to chemotherapy." (PMID 37996927, 2023). "Regarding SIRT3 expression in the studied cases, it showed significant associations with lower apoptotic and higher mitotic index, larger tumour extent and advanced tumour stage." (PMID 37996927, 2023). "Many studies have reported that metabolic programs are linked to tumorigenesis, as SIRT3 is an important mediator of mitochondrial metabolic pathways so its overexpression and down-regulation is also linked to the tumor formation or tumor suppression." (PMID 36809279, 2023). "The expression levels of mitochondria tumor-suppressor and DNA-repair proteins (PGC-1α, TFAM, OGG1, MTUS1, and SIRT3) were examined in tumor samples from patients with OSCC to determine the association of these proteins with patient outcomes." (PMID 37627097, 2023). "How loss of SIRT3 promotes ROS production and mediates an enhanced tumor phenotype remains to be determined." (PMID 35571098, 2022). "For example, SIRT3 was implicated as a tumor suppressor in solid tumor cells such as breast and ovarian cancer cell lines." (PMID 35019856, 2022). "The significant increase in SIRT3/FOXO3a/SOD2 UPRmt axis demonstrated a high risk of tumor progression in head and neck cancer." (PMID 34717757, 2021). "The decreased expression of HIF2α inhibits the expression of NUDT1 at the transcriptional level and causes the degradation of SIRT3 to accelerate, which cause an increase in tumour cell ROS and oxidative stress levels, thereby inhibits the progress of ccRCC." (PMID 34841698, 2021). "On the contrary, SIRT3 acts as a tumor suppressor since reduced SIRT3 expression was associated with B cell proliferation and worsening of patients with B cell malignancies." (PMID 31849939, 2019). "The FoxO3a regulation by SIRT3 has also recently been implicated as a necessary adaptation to the mitochondrial unfolded protein response (mtUPR), which occurs more frequently in tumor cells with accumulating mitochondrial DNA mutations." (PMID 29099803, 2017). "Weighted linear regression analysis informed that the increased tumor cell sensitivity to hypoxia caused by Sirt3 knockdown is significant (p < 0.05)." (PMID 27270321, 2016).